TRPV1 (transient receptor potential cation channel subfamily V member 1)
Diseases named in the same sentence as TRPV1 in open-access papers (continued):
Sharing a sentence is not in itself a finding about the gene and the disease.
small cell lung carcinoma (2 papers, 2020 to 2022). Small cell lung cancer (SCLC) is a highly aggressive malignant neoplasm, accounting for 10-15% of lung cancer cases, characterized byrapid growth, and early metastasis. "Interestingly, in human small cell lung carcinoma cells, the classical TRPV1 agonist capsaicin induces apoptosis via TRPV6, independent of TRPV1, in a Ca2+- and calpain-dependent manner." (PMID 32825277, 2020).
status epilepticus (2 papers, 2020 to 2022). Status epilepticus is defined as a continuous seizure lasting more than 30 min, or two or more seizures without full recovery of consciousness between any of them. "Increased TRPV1 protein levels were detected in the dentate gyrus of mice during the acute and chronic phase of the pilocarpine-induced Status Epilepticus (SE) model." (PMID 35203625, 2022).
systemic inflammatory response syndrome (2 papers, 2021). SIRS is a serious condition related to systemic inflammation, organ dysfunction, and organ failure. "Similar findings have been reported in the context of systemic inflammatory response syndrome (SIRS); whereby TRPV1 nociceptors plays an immunosuppressive role by inhibiting production of TNF-α." (PMID 34975876, 2021).
systemic lupus erythematosus (2 papers, 2021 to 2026). An autoimmune multi-organ disease typically associated with vasculopathy and autoantibody production. "TRPV1 is linked to chronic inflammatory pain and neuropeptide dysregulation in systemic lupus erythematosus (SLE)." (PMID 41569118, 2026). "Substance p which can be released following exposure to capsaicin is a TRPV1 inducer, shown to have altered concentration and function in mice with systemic lupus erythematosus (SLE)." (PMID 34012530, 2021).
transitional cell carcinoma (2 papers, 2012 to 2014). A malignant neoplasm arising from the transitional epithelium, usually affecting the urinary bladder, ureter, or renal pelvis. "Changes in TRPV1 expression occur during the development of transitional cell carcinoma (TCC) of human bladder." (PMID 22523714, 2012). "Changes in the TRPV1 expression can occur during the development of human urothelial cell carcinoma (UCC)." (PMID 22523714, 2012). "In this paper, we report the documented role of TRPV1 in the transitional cell carcinoma (TCC) of human bladder in presence of urothelium impairment and explore the opportunity of considering TRPV1 as a drug target." (PMID 24901005, 2014).
urothelial carcinoma (2 papers, 2016 to 2025). A malignant neoplasm derived from the transitional epithelium of the urinary tract (urinary bladder, ureter, urethra, or renal pelvis). "Furthermore, capsaicin exerts its apoptotic activity through overexpression of transient receptor potential vanilloid type 1 (TRPV1), the most-often mentioned cationic channel protein targets of capsaicin, in urothelial carcinoma cells." (PMID 27367652, 2016).
vascular dementia (2 papers, 2020 to 2024). A degenerative vascular disorder affecting the brain. "Other studies have reported that EA at GV20 reversed behavioral deficit and LTP impairment, possibly through the N-methyl-D-aspartate receptor 1 (NMDA-R1) and TRPV1 pathway, thus reversing NR1- (one of the NMDA receptor subunits) and TRPV1-mediated neurotoxicity in vascular dementia." (PMID 32630156, 2020).
Ventricular arrhythmia (2 papers, 2021 to 2025). "Consequently, FeNCs-TRPV1 reduce cardiac injury and ventricular arrhythmia, enhance the activity of prosurvival kinases, and inhibit myocardial cell apoptosis." (PMID 41387112, 2025).
vitamin D deficiency (2 papers, 2019 to 2021). A nutritional condition produced by a deficiency of VITAMIN D in the diet, insufficient production of vitamin D in the skin, inadequate absorption of vitamin D from the diet, or abnormal conversion of vitamin D to its bioactive metabolites. "Furthermore, we provide evidence supporting the notion that this novel vitamin D/TRPV1 axis may explain some of the beneficial actions of this vitamin in disease states where TRPV1 expression and vitamin D deficiency are known to overlap." (PMID 33825665, 2021). "In mice, vitamin D deficiency increases the production of ROS which activates TRPA1 and TRPV1." (PMID 31731694, 2019).
abscess (1 paper, 2024). An inflammatory process characterized by the accumulation of pus within a newly formed tissue cavity which is the result of a bacterial, fungal, or parasitic infection or the presence of a foreign body. "Treatment with natural inhibitors of TRPA1 with or without blockade of TRPV1 also reduced abscess size." (PMID 39337422, 2024). "While deletion of TRPV1 did not affect lesion size or inflammatory markers, TRPA1−/− mice demonstrated significantly reduced infection severity and abscess size." (PMID 39337422, 2024).
adenomyosis (1 paper, 2016). The growth of endometrial tissue inside the muscular wall of the uterine corpus. "In addition, they are consistent with reported constitutive activation of NF-κB, increased expression of COX-2, TRPV1 and OTR in adenomyosis." (PMID 27724926, 2016).
age-related hearing loss (1 paper, 2025). "Regarding hearing loss, TRPV1 channel-related targets might potentially present novel therapeutic approaches for the prevention and treatment of drug-induced, noise-induced, and age-related hearing loss." (PMID 40688696, 2025).
aging (1 paper, 2023). A developmental process that is a deterioration and loss of function over time. "Furthermore, our results revealed that the increased ROS levels induced by UPM treatment induced transient receptor potential vanilloid 1 (TRPV1) activity, which is related to skin aging and inflammatory responses." (PMID 36827162, 2023).
alcohol abuse (1 paper, 2023). The use of alcoholic beverages to excess, either on individual occasions ("binge drinking") or as a regular practice. "Interestingly, in patients with a long history of smoking and/or alcohol abuse, TRPV1 staining (similar to cancerous tissue) can also be seen in keratinocytes above the basal layer." (PMID 37240443, 2023).
alcoholism (1 paper, 2021). "Blednov and Harris showed that the deletion of TRPV1 in mice altered behavioral effects of ethanol which indicates a connection between TRPV1 and alcoholism." (PMID 33546598, 2021).
aneurysm (1 paper, 2015). Bulging or ballooning in an area of an artery secondary to arterial wall weakening. "The higher mRNA levels of the four receptors (CB1, CB2, TRPV1, and GRP55) show together with differential levels of their ligands in the tissue an activated endocannabinoid system in human aneurysms." (PMID 26539497, 2015). "Therefore, we investigated the components of the endocannabinoid system in human aorta and found significantly higher mRNA levels of the cannabinoid receptors CB1, CB2, TRPV1, and GRP55 in the aneurysms as compared to the samples from controls." (PMID 26539497, 2015).
anxiety disorder (1 paper, 2020). A category of psychiatric disorders which are characterized by anxious feelings or fear often accompanied by physical symptoms associated with anxiety. "In fact, TRPV1 is presently being considered as a target for treating pathophysiological processes including pain, fear, and anxiety disorders." (PMID 32116530, 2020).
apical periodontitis (1 paper, 2022). "We had previously demonstrated that pharmacological ablation of a subpopulation of nociceptors (TRPV1+ neurons) resulted in accelerated bone loss in a model of apical periodontitis in rats." (PMID 35639178, 2022).
aspiration pneumonia (1 paper, 2025). "Inhalation of TRPV1 stimulants has been clinically applied to prevent aspiration pneumonia in elderly people by inducing the pharyngeal reflex." (PMID 40823821, 2025).
autonomic dysreflexia (1 paper, 2012). A syndrome associated with damage to the spinal cord above the mid thoracic level (see SPINAL CORD INJURIES) characterized by a marked increase in the sympathetic response to minor stimuli such as bladder or rectal distention. "Given the specific effects of T3 SCI on TRPV1-positive afferents, we hypothesized that these afferents contribute to autonomic dysreflexia (AD)." (PMID 22934013, 2012).
B-cell non-Hodgkin lymphoma (1 paper, 2022). The most common type of non-Hodgkin lymphoma. "TRPV1 was also detected in all 49 patients including B-cell non-Hodgkin’s lymphoma (B-NHL), MM, and others and 20 healthy controls." (PMID 35477804, 2022).
bacteremia (1 paper, 2021). "On the other hand, a significantly higher ratio of bacteremia was observed in TRPV4 KO mice (15 out of 31 mice, 48.4%) compared with wild-type (3 out of 20 mice, 15%) and with TRPV1 KO mice (4 out of 14 mice, 28.6%) by high-dose inoculation." (PMID 34804016, 2021).
bacterial pneumonia (1 paper, 2021). Acute infection of the lung parenchyma caused by bacteria (e.g., Streptococcus pneumoniae, Haemophilus influenzae, Chlamydia pneumoniae, Mycoplasma pneumoniae, and Legionella pneumophila). "TRPV1 neuron depletion and CGRP antagonism has been proven to be favorable in animal models of bacterial pneumonia as TRPV1+ sensory neurons suppressed protective immune responses through CGRP release." (PMID 34975876, 2021).
basophilic leukemia (1 paper, 2017). "For instance, the transcripts of TRPV1, TRPV2, TRPV4, and TRPV6 were identified in RBL-2H3 cells (rat basophilic leukemia cell line), TRPV1, TRPV2, and TRPV6 in HMC-1, and TRPV2 in human lung, skin, and cord blood-derived mast cells." (PMID 28158279, 2017).
benign prostate hyperplasia (1 paper, 2014). "Moreover, alpha1D-AR and TRPV1 colocalization was investigated by confocal microscopy in PCa cell lines and by fluorescence microscopy in benign prostate hyperplasia (BPH) and PCa tissues." (PMID 25481381, 2014). "The expression of TRPV1 has been found to be significantly up-regulated in PCa compared with benign prostate hyperplasia (BPH) tissues, and the increased expression of TRPV1 correlates with increasing PCa tumour grade." (PMID 25481381, 2014).
bipolar disorder (1 paper, 2018). A disorder of the brain that causes unusual shifts in mood, energy, activity levels and the ability to carry out day-to-day tasks. "The variants are in the Npas2, Cp, Polr3c, Smarca4, Trpv1, and Slc5a7 genes, and many of these genes’ products are in pathways implicated in human bipolar disorders." (PMID 29768498, 2018).
Bladder Disorders (1 paper, 2022). "In conclusion, there is a rationale for the selective blockade of TRPV1 channels for various bladder disorders." (PMID 36135835, 2022).
bone metastasis (1 paper, 2025). Transfer of a neoplasm from its primary site to bones. "Activation of TRPV1 leads to the development of metastatic bone pain, release of proinflammatory substances, and sensitization of nociceptive neurons, which may exacerbate bone metastasis-induced pain." (PMID 41010313, 2025).
Cachexia (1 paper, 2023). Severe weight loss, wasting of muscle, loss of appetite, and general debility related to a chronic disease. "Since weight loss is one of the characteristics of cancer cachexia 36, these results suggest that blockade of TRPV1 activation may prevent the development of cachexia, thereby prolonging survival." (PMID 37461623, 2023).
CADASIL (1 paper, 2019). "Molecular systems that have been implicated in CADASIL patients include decreased TRPV1 channel expression, altered PDGF signaling, and oxidative stress." (PMID 31647781, 2019).
central nervous system infection (1 paper, 2025). "The effect of intranasal TRPV1 stimulation was dominant on the olfactory nerve and could suppress central nervous system infection via the nose-to-brain route." (PMID 40823821, 2025). "Intranasal TRPV1 stimulation inhibited intracranial invasion and could control lethal central nervous system infection by S. pneumoniae." (PMID 40823821, 2025).
cerebral malaria (1 paper, 2019). A sequestration of Plasmodium falciparum in the brain, which can cause coma and/or seizures. "Here, plasma and cerebral TNFα and IL-6 production was markedly diminished by TRPV1 ablation, thus evidencing, once more, that TRPV1 signaling is involved in the tissue damage associated with cerebral malaria." (PMID 31223430, 2019). "We initially investigated whether infection with P. berghei ANKA, a plasmodium strain known to cause cerebral malaria in mice, influences TRPV1 expression in the mouse brain." (PMID 31223430, 2019). "Here, we used TRPV1 wild-type (WT) and knockout (KO) mice to evaluate the role of TRPV1 in cerebral malaria." (PMID 31223430, 2019). "Overall, the data presented here, indicate that TRPV1 channels contribute to the development and outcome of cerebral malaria." (PMID 31223430, 2019). "We next assessed whether the ablation of TRPV1 influences cerebral malaria progression and mortality." (PMID 31223430, 2019). "However, the relevance of TRPV1 to the brain inflammation and symptoms of cerebral malaria has never been investigated." (PMID 31223430, 2019). "Here, we show for the first time that in the absence of TRPV1, P. berghei ANKA infection does not progress into cerebral malaria in the majority of the infected mice, protecting them from death and from the development of any disease symptoms and signals apart from blood parasitaemia." (PMID 31223430, 2019).
cervical squamous cell carcinoma (1 paper, 2022). A squamous cell carcinoma arising from the cervical epithelium. "In this study, we found a significant reduction of TRPV1 expression in cervical squamous cell carcinoma and this expression is inversely association with the risk of cervical squamous cell carcinoma." (PMID 36072430, 2022). "We analyzed the correlation between TRPV1 and immune cells in cervical squamous cell carcinoma, and found that TRPV1 was positively correlated with T cell immune infiltration, and negatively correlated with macrophages and NK cells." (PMID 36072430, 2022). "That means TRPV1 is involved in the regulation of multiple mechanisms in the occurrence of cervical squamous cell carcinoma." (PMID 36072430, 2022). "Furthermore, TRPV1 is involved in cell differentiation, iron death, inflammatory response, and metabolic regulation in cervical squamous cell carcinoma." (PMID 36072430, 2022). "We speculate that TRPV1 may participate in tumor immunologic escape through regulating the infiltration of immune cells, and thus participate in the occurrence of cervical squamous cell carcinoma." (PMID 36072430, 2022).
childhood asthma (1 paper, 2016). "The TRPV1 genetic variant has been shown to be associated with a lower risk of childhood asthma or the presence of wheezing." (PMID 27255083, 2016). "For example, TRPV1 polymorphism has been associated with childhood asthma and a loss of function." (PMID 27255083, 2016).
chondropathy (1 paper, 2013). "In addition, associations between spinal expression of GFAP, TRPV1 and COX2 mRNA and macroscopic chondropathy score were also determined in these cases." (PMID 24282543, 2013).
chronic heart failure (1 paper, 2018). "Finally, the literature reports that exercise training partially prevented the decreased of TRPV1 in DRG afferents in rats with chronic heart failure." (PMID 30483115, 2018).
Clear Cell Renal Cell Carcinoma (1 paper, 2020). "Differential expression of TRPV1 has been detected in many cancer types, including clear cell renal cell carcinoma (ccRCC)." (PMID 32913462, 2020).
cocaine addiction (1 paper, 2019). "Our results support behavioral analyses with selective cannabinoid, TRPV1 or PPAR-α receptor ligands to control cocaine addiction." (PMID 30901889, 2019).
colonic adenocarcinoma (1 paper, 2023). "By contrast, TRPV1-mediated neurogenic inflammation was reported to protect mice from colonic adenocarcinoma." (PMID 37371563, 2023).
colorectal adenocarcinoma (1 paper, 2021). The most common type of colorectal carcinoma. "The expression levels of four inflammation-related genes (TRPV1, iNOS, IL-1β, and IL-8) were decreased significantly (p < 0.05) in the human colorectal adenocarcinoma Caco-2 cells treated with three different concentrations (12.5, 25, and 50 mg/L) of PS-MPs for 24 and 48 h." (PMID 34809705, 2021).
cryptorchidism (1 paper, 2025). The failure of one or both testes of a male fetus to descend from the abdomen into the scrotum during the late part of pregnancy. "Given our observation of high TRPV1 expression in spermatocytes, we further investigated the molecular mechanisms underlying TRPV1-induced spermatocyte apoptosis in cryptorchidism." (PMID 40180900, 2025). "In this study, we determined that TRPV1 is predominantly expressed in the spermatocytes of the mouse testis and plays an important role in spermatogenic injury caused by cryptorchidism." (PMID 40180900, 2025). "In this study, we observed the phenotype of Trpv1−/− cryptorchid mice and found that TRPV1 knockout can alleviate the reduction in sperm count, damage to the seminiferous epithelium, and spermatogenic apoptosis caused by cryptorchidism." (PMID 40180900, 2025). "In order to clarify the role of TRPV1 in spermatogenic damage caused by cryptorchidism, we further constructed the cryptorchid model of Trpv1−/− mice, and found that there were obvious phenotypic differences between Trpv1−/− mice and WT mice after cryptorchidism." (PMID 40180900, 2025). "Moreover, our investigation of TRPV1 expression at 9 days of cryptorchidism revealed a significant increase in its levels within cryptorchid testes, which suggests that TRPV1 may be involved in spermatogenic cell damage caused by cryptorchidism." (PMID 40180900, 2025). "Herein, we first observed the expression pattern of TRPV1 in the testes of mice with experimental cryptorchidism, and then investigated the role and mechanism of TRPV1 in spermatogenic cell apoptosis by using Trpv1−/− mice." (PMID 40180900, 2025). "Threrfore, our results suggest that TRPV1 is involved in spermatocyte apoptosis in mice with cryptorchidism through both intrinsic mitochondrial-mediated pathway and extrinsic death receptor-mediated pathway." (PMID 40180900, 2025). "This study demonstrates for the first time that TRPV1 plays an important role in spermatogenic cell apoptosis after cryptorchidism, providing a new target for the treatment of cryptorchidism." (PMID 40180900, 2025). "Hence, we conclude that TRPV1 can induce the increased expression of apoptosis-related molecules in the mouse model of cryptorchidism to participate in spermatocyte apoptosis." (PMID 40180900, 2025). "The results showed that TRPV1 was highly expressed on the membrane of spermatocytes in mouse testis, and the expression increased significantly in the testis of mice with experimental cryptorchidism." (PMID 40180900, 2025). "However, whether TRPV1 is involved in spermatogenic cell apoptosis induced by cryptorchidism remains unclear." (PMID 40180900, 2025).
dependence (1 paper, 2019). "Undoubtedly, additional studies are necessary to reveal the exact role of TRPV1 in the expression and development of morphine dependence." (PMID 31998461, 2019).
diffuse large B-cell lymphoma (1 paper, 2022). "However, TRPV1 was increased in 2 females diagnosed with diffuse large B-cell lymphoma, who were under-treatment (one with radiation only and the latter on Rituximab)." (PMID 35477804, 2022).